IFI16 (interferon gamma inducible protein 16)
Diseases named in the same sentence as IFI16 in open-access papers (continued):
Sharing a sentence is not in itself a finding about the gene and the disease.
infection (continued). "Given our observed interactions between the PY domain and many components of the nuclear pore complex (NPC) during infection, it may be that binding of the viral capsid and subsequent release of the viral DNA induces structural changes at the NPC which actively recruit local IFI16 via PY." (PMID 27935834, 2016). "Using a FISH assay, they demonstrated that during HSV-1 (strain 17+) infection of U2OS cells (5 PFU/cell) containing transfected IFI16-EGFP construct, virion DNA colocalized only with full length IFI16-EGFP with intact NLS and not with mutated NLS-IFI16-EGFP that were localized in the cytoplasm." (PMID 26134128, 2015). "In the absence of infection, 6A-IFI16-GFP mutant transiently expressed in HFFs lost the ability to form puncta or filaments, whereas the 6D-IFI16-GFP displayed normal or even enhanced puncta and filament formation compared to WT IFI16." (PMID 37283074, 2023). "We establish that phosphorylation does not impact the initial recruitment of IFI16 to viral genomes, but rather its progression through stages of LLPS from puncta to filaments as infection progresses." (PMID 37283074, 2023). "VSV-Sp100A infection in PML−/− and Sp100−/− cells induced significantly higher levels of transcription from RIG-I, OAS-2, IFI16, and IFN-β genes than VSV-GFP did but not transcription from the control gene c-myc." (PMID 36383022, 2022). "Infection with the highly attenuated VACV strain MVA, but not with VACV-WR, induced IFI16-dependent CCL5 and ISG56 expression." (PMID 34356829, 2021). "In keeping with previously published reports, IFI16 was not decreased at 4 hours post infection with HSV-1, but IFI16 was decreased after 24 hours of infection." (PMID 32101570, 2020). "Then again, we cannot rule out an involvement of IFI16 in sensing the dual infection and the cooperation of this sensor with cGAS in the activation of the antiviral IFN-β responses since block of IFI16 decreased the IFN-β response." (PMID 31867020, 2019). "Moreover, we also observed consistent phenomena in HSV-1-infected A549 cells with IFI16-/-, IFI16-/—STING knockdown or IFI16-/—cGAS knockdown, indicating that IFI204 might facilitate cGAS-STING DNA sensing pathway that leads to IRF3 activation during the infection of HSV-1." (PMID 31603949, 2019). "In agreement, overexpression of IFI16 in a Flp-In 293 inducible system reduced viral and BFP protein levels during infection with RF, but not WT, HSV-1::bfp." (PMID 27935834, 2016). "Knockdown of H2B impaired the IFI16-mediated IFN-β response during KSHV and HSV-1 de novo infection and did not affect IFI16-inflammasome induction." (PMID 27764250, 2016). "However, the fate of nuclear IFI16 during HSV-1 infection, whether IFI16 undergo acetylation during HSV-1 infection, the role of p300 during viral DNA recognition in the nucleus, and the mechanism behind the IFI16 redistribution into the cytoplasm during infection was not studied." (PMID 26134128, 2015). "In the absence of IFI16, HSV-1 promoter occupancy by H3K9me9 did not change significantly over the course of the 4 hour infection." (PMID 25375629, 2014). "Together, these observations uncover a previously unknown interaction between IFI16 and HDAC1/2 in cells under normal physiological conditions, regardless of their infection status, and propose a potential link between IFI16 and the KSHV latency protein LANA." (PMID 39927772, 2025). "In the present study, we observed that several ISGs with known or proposed anti-CCHFV activity, i.e., Mx1, ISG15 and ISG20 or not defined for CCHFV like IFIT1, IFIT3, IFITM3, IFI16, and OAS3 were upregulated in the acute phase CCHFV patient samples as well as in the cell-infection model." (PMID 35437144, 2022). "HSV-1EdU or ΔICP0EdU infection of shCtrl cells recapitulated observations made in parental HFt cells, demonstrating that lentiviral transduction, shRNA expression, or puromycin selection did not affect PML-NB entrapment of vDNA or alter IFI16 localization." (PMID 29309427, 2018).
infection (continued). "For example, initial studies indicated that IFI16 was degraded by ICP0 during HSV-1 infection, but it later emerged that the degradation could occur in the absence of ICP0 in conditions in which the mutant infection was progressing as rapidly as the wt." (PMID 26200910, 2015).
tumor (65 papers, 2010 to 2026). "IFI16 plays a crucial role in immune surveillance and tumor regulation through its inflammasome‐associated “sensing‐response” mechanism." (PMID 41316520, 2025). "Conversely, elevated levels of IFI16 in the serum of BC patients are associated with pro-tumor inflammation and disease progression." (PMID 39744568, 2025). "Overexpression of IFI16 has been implicated in the activation of the inflammasome, leading to the induction of IL-1β production in the tumor microenvironment of PAAD." (PMID 40386782, 2025). "The tumor-suppressive functions of IFI16 are closely linked to its unique DNA-binding capacity, particularly its interactions with single-stranded DNA (ssDNA) and cruciform structures." (PMID 40386782, 2025). "In contrast, the IFI16-induced STING pathway reportedly promotes tumor growth by causing an infiltration of immunosuppressive cells such as regulatory T cells." (PMID 37998338, 2023). "The tumor suppressor function is mediated via IFI16 associating with other proteins, particularly via the pyrin domain of IFI16 which facilitates protein–protein interactions." (PMID 31333597, 2019). "The role of IFI16 in tumor biology and the underlying mechanisms in various tumor types." (PMID 40386782, 2025). "Moreover, another study showed that in addition to ICP0-mediated degradation, vhs-dependent targeting of IFI16 mRNA promotes complete loss of IFI16 in tumor-derived human cells." (PMID 36986359, 2023). "Further systemic investigation is required to determine whether dsDNA breakdown caused by gemcitabine majorly dominates the upregulation of IFI16 in cancer cells and reshapes the tumor microenvironment by increasing the TAM population in PAAD." (PMID 34150748, 2021). "However, the IFI16 pathway has also been implicated in tumor drug resistance." (PMID 38523155, 2024). "Specifically, IFI16 promotes apoptosis of tumor cells, inhibits neovascularization, and enhances the recruitment of CD68/CD14-positive macrophages through the release of chemotactic factors." (PMID 40386782, 2025). "In the context of estrogen receptor (ER)-positive BC, IFI16 plays a pivotal role in augmenting tumor growth by facilitating the transcriptional activation of aromatase and subsequent E2 production in adipose tissue." (PMID 40386782, 2025). "Collectively, these findings underscore the nature of IFI16 in BC, with its tumor suppressive properties being counterbalanced by its potential to elicit an immunosuppressive TME." (PMID 40386782, 2025). "Collectively, these findings underscore the importance of IFI16 as a tumor suppressor in HCC and its potential therapeutic implications." (PMID 40386782, 2025). "The results indicated that the tumor volume and weight were significantly higher in the IFI16 overexpression group compared to the control group." (PMID 38831470, 2024). "In vitro, IFI16 promoted ccRCC cell proliferation, migration, and invasion, while in vivo, it facilitated subcutaneous tumor growth and the formation of lung metastatic foci." (PMID 38831470, 2024). "injected SiHa cells into NOD/SCID mice to establish tumour xenografts and verify the roles of PD-L1 and IFI16 in CC development." (PMID 39735605, 2024).
tumor (continued). "Overexpression of IFI16 reduced cell viability, which led to significant inhibition of tumor growth and reduction of tumor size in HCC cells." (PMID 37081882, 2023). "The major CD1 murine ortholog Cd1d1 and the IFI16 murine ortholog Ifi204 are repressed in Myc-CaP tumor cells, compared with normal prostate tissues dissected from isogenic FVB mice." (PMID 37327786, 2023). "Significant SNV alterations were observed in BRCA2, ACACB, BRCA1, MSH6 and IFI16 in most tumour types." (PMID 37660060, 2023). "Immunohistochemistry revealed that high IFI16 expression in human ESCC tissues tended to be associated with disease-free survival and was significantly associated with tumor depth, lymph node metastasis, and macrophage infiltration." (PMID 37998338, 2023). "The clinicopathological data of the patients in the two groups were compared, and the progressive depth of tumor invasion (p = 0.042) and positive lymph node metastasis (p = 0.039) significantly correlated with a high expression of IFI16." (PMID 37998338, 2023). "Thus, ectopically restored expression of either CD1 or IFI16 murine orthologs in cancer cells with DNA hypomethylation-induced silencing suppresses tumor formation, a finding only evident in immune competent mice, and associated with evidence of selectively increased anti-tumor activity." (PMID 37327786, 2023). "Several tumor suppressor genes are in this part of chromosome 1, including HRPT2, MDA7/IL-24, IFI16, and thus promoting tumor proliferation and growth." (PMID 36830839, 2023). "IFI16 has been reported to form an inflammasome by binding to an NOD-like receptor involved in tumor progression." (PMID 37998338, 2023). "Re-expression of CD1 or IFI16 murine orthologs in immunocompetent mice abrogates tumorigenesis, accompanied by activation of anti-tumor immunity." (PMID 37327786, 2023). "The tissues were divided into IFI16-high and IFI16-low groups depending on the staining intensity of IFI16 in the invasive area of the tumor." (PMID 37998338, 2023). "The significant increase of IFI16 expression in the high metastatic potentials 30M cell and tumor tissues hinted us to investigate its role in metastasis regulation both in vitro and in vivo." (PMID 35371314, 2022). "For the tumor sphere formation assay and limiting dilution assay, overexpression of IFI16 and HuR both restored the self-renewal and tumorigenesis ability of sh-ARPC1B GSCs, respectively." (PMID 36380368, 2022). "In summary, the present research identified IFI16 as a signature that can predict the overall survival and affect the tumor immune microenvironment of SKCM." (PMID 34930258, 2021). "Bioinformatic analysis showed that the expression levels of IFI16 were related to clinicopathological parameters: IFI16 was highly expressed in ccRCC patients with lymph node metastasis, higher tumor stages, and higher histopathological grades." (PMID 33659024, 2021). "To understand how IFI16 overexpression in PAAD cells regulates the TAM population in the tumor microenvironment, we collected the culture supernatant from PAAD cells with or without IFI16 overexpression." (PMID 34150748, 2021). "To further identify the role of TAMs in IFI16 overexpression-induced PAAD tumor growth and progression, we used liposome clodronate to deplete TAMs from mice bearing orthotopic PAAD." (PMID 34150748, 2021). "Overexpression of IFI16 in tumor cells activated inflammasome machinery, thereby inducing the production of IL-1β and causing maturation, proliferation, and migration of TAMs in the tumor microenvironment." (PMID 34150748, 2021).
tumor (continued). "Knockdown of IFI16 or treatment with gemcitabine moderately reduced the growth rate of orthotopic tumors of PAAD in mice, while the efficacy of gemcitabine in suppressing PAAD tumor was largely improved when IFI16 was knocked down." (PMID 34150748, 2021). "The weight of the tumor was then measured, which indicated that IFI16 overexpression remarkably increased the tumor weight." (PMID 34150748, 2021). "Removal of TAMs using liposome clodronate attenuated IFI16 overexpression-induced tumor growth in PAAD." (PMID 34150748, 2021). "Depletion of TAMs by injection of liposome clodronate attenuated the IFI16 overexpression-induced tumor growth in PAAD." (PMID 34150748, 2021). "The IHC staining also demonstrated that IFI16 expression level was significantly correlated with the location of tumor (p < 0.05)." (PMID 34930258, 2021). "Most studies have focused on the effects of IFI16 on the growth and migration of tumor in HNSCC tissue or cell lines." (PMID 32577124, 2020). "IFI16 is a nuclear protein involved in a variety of physiological processes, including cell cycle regulation, tumor suppression, and virus sensing." (PMID 32903274, 2020). "We also noted that some proliferation-associated genes in tumor cells were also significantly regulated by CRNDE knockdown, including IGFBP4, ANXA1, KLF6, AATF, and IFI16." (PMID 33298855, 2020). "Since its discovery in the early 90s, IFI16 has been involved in a growing number of physiological processes, such as cell cycle regulation, tumor suppression, apoptosis, DNA damage signaling, virus sensing and virus restriction." (PMID 32903274, 2020). "Overall, these data indicate that IFI16 exerts an anti-tumoral activity in vivo by stimulating apoptosis of tumor cells, impairing neo-vascularization, and releasing chemotactic factors, which in turn recruit macrophages." (PMID 31861809, 2019). "IFI16 has an additional role as a tumor suppressor and thus its absence in NCCIT also removes an important check on tumorigenesis." (PMID 31333597, 2019). "Necrotic changes positively correlated with anti-angiogenic role of IFI16 demonstrated by analyzing the tumor microvessel density." (PMID 31861809, 2019). "This study provides an exciting expositional framework for future studies concerning the role of p204, and its human counterpart IFI16, in anti-tumor immune response." (PMID 29691417, 2018). "This is particularly interesting as both IFI16 and MNDA have been implicated as tumor suppressors, functioning as regulators of cell cycle and apoptotic processes." (PMID 25665578, 2015). "One possibility is that in the HPV related oropharyngeal SCC (OPSCC), the expression of IFI16 protein is upregulated and contributing to the inhibition of tumor progression." (PMID 23956879, 2013). "Interestingly, while IFI16 primarily exerts its tumor-suppressive effects through nuclear DNA surveillance, elevated serum levels of this protein have paradoxically been associated with poor prognosis in BC patients." (PMID 40386782, 2025). "Therefore, we have reason to believe that IFI16 plays a crucial role in ccRCC tumor occurrence and metastasis within the body." (PMID 38831470, 2024). "Furthermore, elevated IFI16 expression correlates closely with higher tumor grade, stage, and poorer prognosis." (PMID 38831470, 2024). "Furthermore, tumor patients with high IFI16 expression had better overall survival and immunotherapy outcomes." (PMID 38831059, 2024). "Both PD-L1 and IFI16 knockdown significantly suppressed the growth of SiHa-derived tumours in vivo." (PMID 39735605, 2024).
tumor (continued). "In addition, transplantation of the IFI16-knockdown ESCC cell line into mice suppresses tumor growth." (PMID 37998338, 2023). "Caspase-1 inhibitor (Ac-YVAD-CMK) could effectively inhibit the tumor suppressive effect of IFI16, thus it can be speculated that the tumor suppressive effect of IFI16 may be closely related to caspase-1-mediated pyroptosis." (PMID 37081882, 2023). "In addition, IFI16 shows antitumor effects by inhibiting DNA repair in tumor cells via STING-induced type I interferon signaling." (PMID 37998338, 2023). "Our defined PRMT1-cGAS signaling axis might partially explain the synergistic effect of inhibition of PRMT1 and PRMT540, in which both the parallel cGAS and IFI16 signaling might be activated to maximal downstream cascade to trigger anti-tumor immunity." (PMID 37193698, 2023). "The tumor-promoting and tumor-suppressive roles of IFI16 have been evaluated in various cell lines." (PMID 37998338, 2023). "IFI16 also increased in ESCC tumor compared with non-tumor tissue." (PMID 35371314, 2022). "It was even found that IFI16 expression was reduced in liver cancer and may act as a tumor suppressor gene by triggering cell apoptosis and inhibiting cell proliferation." (PMID 34150748, 2021). "The size, as well as weight, of the representative tumor also suggested that IFI16 overexpression could be neutralized upon TAM clearance." (PMID 34150748, 2021). "IFI16 may play opposite roles in different tumor types, and few studies have explored the biological function of IFI16 in RCC." (PMID 33659024, 2021). "Neutralization of IL-1β abolished the effect of IFI16-overexpressing tumor cells on TAMs." (PMID 34150748, 2021). "Taken together, these observations suggest that IFI16 overexpression promotes tumor growth and progression of PAAD and may play a role in regulating TAMs in the tumor microenvironment." (PMID 34150748, 2021). "Since IFI16 overexpression was reported to trigger innate immune cells, we measured whether IFI16 overexpression in PAAD altered the immune cell profile in the tumor microenvironment." (PMID 34150748, 2021). "Therefore, in our study, we studied the effect of depletion of the whole TAM population on IFI16-mediated tumor growth because the specific removal of either subtype of TAMs is perceptually and technically difficult." (PMID 34150748, 2021). "Gemcitabine could activate the tumor inflammasome, at least partially, by upregulating IFI16 expression." (PMID 34150748, 2021). "When the expression of IFI16 in tumor cells is knocked down, this effect is reversed." (PMID 33659024, 2021). "Overexpression of IFI16 in Panc-2 cells significantly accelerated tumor growth by a week." (PMID 34150748, 2021). "Overexpression of IFI16 significantly promoted tumor growth, increased tumor size and weight in the experimental PAAD model of mice, and specifically increased the population of tumor-associated macrophages (TAMs) in the tumor microenvironment." (PMID 34150748, 2021). "In addition, high IFI16 levels positively correlated with lymphatic metastasis, tumor stage, and histopathological grade." (PMID 33659024, 2021). "Additionally, knockdown of IFI16 in gemcitabine-treated PAAD tumors reduced TAM infiltration in the tumor microenvironment, improving gemcitabine sensitivity." (PMID 34150748, 2021). "IFI16 protein expression level is correlated with tumor location (p < 0.05)." (PMID 34930258, 2021). "An in vivo study showed that restored expression of IFI16 could effectively promote tumor regression, which could be partly abrogated by inhibition of the induced inflammasome in HCC." (PMID 33006365, 2020).